RNA5SP525 (RNA, 5S ribosomal pseudogene 525)
Gene: Ribosomal RNA gene on chromosome X (151,026,295 to 151,026,406, reverse strand). Ensembl gene ENSG00000212595.
Homologues: Orthologues: chimpanzee 5S_rRNA (98% identical). Paralogues in human: RNA5S1 (66% identical), RNA5S10 (66% identical), RNA5S11 (66% identical), RNA5S12 (66% identical), RNA5S13 (66% identical), RNA5S14 (66% identical), RNA5S15 (66% identical), RNA5S16 (66% identical), RNA5S17 (66% identical), RNA5S2 (66% identical), RNA5S3 (66% identical), RNA5S4 (66% identical), and 26 more.